TIMP1 (TIMP metallopeptidase inhibitor 1)
Diseases named in the same sentence as TIMP1 in open-access papers (continued):
Sharing a sentence is not in itself a finding about the gene and the disease.
autoimmune thyroid disease (2 papers, 2011 to 2025). Inflammatory disease of the thyroid gland due to autoimmune responses leading to lymphocytic infiltration of the gland. "Levels of ICAM-1, vascular cell adhesion molecule-1 (VCAM-1), and tissue inhibitor of metalloproteinases 1 (TIMP-1) were significantly higher in patients with functional abnormality due to the autoimmune thyroid disease than in euthyroid subjects." (PMID 22654557, 2011). "A research investigation revealed that autoimmune-mediated dysthyroidism is linked to elevated levels of vascular cell adhesion molecule 1 (VCAM-1), intercellular adhesion molecule-1 (ICAM-1), and TIMP-1 in peripheral blood when compared to cases of non-autoimmune thyroid disease." (PMID 40095713, 2025).
benign ovarian tumors (2 papers, 2010 to 2012). "High TIMP-2 expressions have been found in malignant tumors compared to borderline and benign ovarian tumors while various expressions were observed for TIMP-1 in the same figure." (PMID 22200690, 2012). "The assessment of serum concentrations of TIMP-1 (and some metalloproteinases) appeared to be useful in differentiating between malignant, borderline and benign ovarian tumours although some overlaps between the groups were apparent." (PMID 20459644, 2010).
benign prostatic hyperplasia (2 papers, 2013 to 2017). A non-cancerous nodular enlargement of the prostate gland. "We conclude that tissue levels of MMP3 and MMP7 (finely regulated by their inhibitors TIMP1 and TIMP2) are altered in PCa compared to benign prostatic hyperplasia, which is of special relevance in elderly men." (PMID 28471417, 2017).
bone metastasis (2 papers, 2006 to 2022). Transfer of a neoplasm from its primary site to bones. "The levels of MIP-1δ, MCP-2, TIMP-1, RANTES, IGFBP3, and TNF-α showed significant differences in the pairwise comparative analysis and may therefore mediate pain associated with bone metastasis." (PMID 35845981, 2022). "In addition, MIP-1δ, MCP-2, TIMP-1, RANTES, IGFBP3, and TNF-α expression levels were significantly different between the preradiotherapy and postradiotherapy groups and may thus be closely associated with bone metastasis-related pain." (PMID 35845981, 2022).
cerebral malaria (2 papers, 2013 to 2025). A sequestration of Plasmodium falciparum in the brain, which can cause coma and/or seizures. "In vivo, mice with cerebral malaria (CM) display high levels of both MMP-9 and TIMP-1, and in human patients TIMP-1 serum levels directly correlate with disease severity." (PMID 23967215, 2013).
chondropathy (2 papers, 2013 to 2022). "Both VEGF and TIMP-1 are upregulated in patients with OA, and higher scores are associated with greater chondropathy." (PMID 24108368, 2013).
coagulation disorders (2 papers, 2009 to 2017). "In contrast, TIMP-1 positively correlated with SOFA, lactic acid, and markers of coagulopathy (all p < 0.001)." (PMID 19799791, 2009). "Additionally, TIMP1 regulates the function of other non-MMP enzymes, which have been recently implicated in coagulation disorders and prothrombotic state." (PMID 28192449, 2017).
Cognitive impairment (2 papers, 2020). Abnormal cognition is characterized by deficits in thinking, reasoning, or remembering. "Multiple‐adjusted spline regression models showed linear associations between TIMP‐1 concentrations and cognitive impairment (P value for linearity < 0.01)." (PMID 32431079, 2020). "Multivariable‐adjusted spline regression models showed linear associations between serum TIMP‐1 and cognitive impairment defined by both MMSE (P for linearity = 0.002) and MoCA (P for linearity = 0.0001) score." (PMID 32431079, 2020). "The mechanisms underlying the relationship of serum TIMP‐1 with cognitive impairment so far is unclear, but previous studies have provided some physiological pathways." (PMID 32431079, 2020). "In the present prospective study, we found significant relationships between serum TIMP‐1 levels and the risk of cognitive impairment, independently of age, education levels, medical history and other confounders." (PMID 32431079, 2020). "Participants with both higher TIMP‐1 and matrix metalloproteinase‐9 levels simultaneously had highest risk of cognitive impairment." (PMID 32431079, 2020). "Higher serum TIMP‐1 levels were associated with increased risk of cognitive impairment after acute ischaemic stroke, independently of established risk factors." (PMID 32431079, 2020). "And the ordinal analysis suggested significant associations between serum TIMP‐1 and cognitive impairment severity, the ORs were 1.58 (95% CI, 1.01‐2.48; P trend = 0.020) for MMSE and 1.67 (95% CI, 1.07‐2.61; P trend = 0.008) for MoCA, when two extreme quartiles were compared." (PMID 32431079, 2020). "This limited us to explore the association between TIMP‐1 changes and cognitive impairment." (PMID 32431079, 2020). "However, when cognitive impairment defined by MoCA, we found that education year modified the association between TIMP‐1 and cognitive impairment (P = 0.042 for interaction)." (PMID 32431079, 2020). "Here, our prospective study verified this hypothesis, serum TIMP‐1 was associated with subsequent cognitive impairment among acute ischaemic stroke patients, and provided additional predictive value beyond established risk factors for cognitive impairment." (PMID 32431079, 2020). "In age, sex and education level‐adjusted logistic models, the ORs of cognitive impairment were significantly higher among participants with TIMP‐1 levels in the highest quartile (≥220.6 ng/mL) compared with those in the lowest quartile (<154.4 ng/mL)." (PMID 32431079, 2020). "Compared with the first quartile of TIMP‐1, the multivariate‐adjusted odds ratios (95% confidence intervals) for the highest quartile were 1.80 (1.09‐2.97) for cognitive impairment defined by MMSE and 2.55 (1.49‐4.35) by MoCA." (PMID 32431079, 2020). "The addition of TIMP‐1 to models including conventional factors improved reclassification for cognitive impairment, as shown by net reclassification index or integrated discrimination improvement (P < 0.05)." (PMID 32431079, 2020). "The rate of cognitive impairment was higher among patients with higher TIMP‐1 levels than that patients with lower TIMP‐1 levels." (PMID 32431079, 2020). "For example, Hanzel et al32 found that TIMP‐1 levels in CSF of patients with mild cognitive impairment were higher than the subjective cognitive impairment patients." (PMID 32431079, 2020). "In addition, we also examined the joint effect of serum TIMP‐1 and MMP‐9 on the risk of subsequent cognitive impairment." (PMID 32431079, 2020). "After further adjustment for clinical features, medical histories and other covariates in model 3, compared with the lowest quartile of TIMP‐1, the ORs for the highest quartile were 1.80 (95% CI, 1.09‐2.97) for cognitive impairment defined by MMSE and 2.55 (95% CI, 1.49‐4.35) by MoCA." (PMID 32431079, 2020). "All these studies suggested a potential role of TIMP‐1 in the development of cognitive impairment." (PMID 32431079, 2020).
Cognitive impairment (continued). "In addition, the sensitivity analysis (model 4) suggested that further including randomized treatment in the model 3 did not change the significant association between serum TIMP‐1 and post‐stroke cognitive impairment." (PMID 32431079, 2020). "Third, two evaluations scales were used for cognitive impairment assessment, the consistent findings based on MMSE and MoCA indicated the robustness of the relationship between serum TIMP‐1 and cognitive impairment." (PMID 32431079, 2020).
colorectal adenocarcinoma (2 papers, 2013 to 2025). The most common type of colorectal carcinoma. "TIMP1 was overexpressed in both liver and peritoneal metastases from patients with colorectal adenocarcinoma)." (PMID 23548070, 2013).
congenital heart anomalies (2 papers, 2023 to 2025). "The results of our study and those of related studies indicate that MMP-2, MMP-9, TIMP-1, and according to our findings, also TIMP-2, play a role in the etiopathogenesis of VSD and other congenital heart anomalies in humans." (PMID 39466144, 2025). "Novel approaches, such as coating PTFE shunts with agents specifically suppressing pathways around EGF/EGFR and TIMP-1/MMP-9, might significantly reduce neointimal hyperplasia in SP shunts and therefore improve the outcome of children with complex and congenital heart defects." (PMID 36867212, 2023).
coronary atherosclerosis (2 papers, 2021). Atherosclerosis of the coronary vasculature. "Another author found that patients with CAD had higher MMP‐9 and TIMP‐1 plasma levels but a lower TIMP‐2 level, also both increased MMP‐9 and TIMP‐ 1 plasma levels in premature coronary atherosclerosis patients, but with lower MMP‐3 and TIMP‐2 levels." (PMID 33381894, 2021).
dental pulp inflammation (2 papers, 2020 to 2022). "On the other hand, there is a more increased release of active MMPs in pulpitis than in healthy pulp tissue, indicating their role in pulp inflammation: released cytokines (IL-1β) and tumor necrosis factor-α (TNF-α) in pulp inflammation, activate MMP-1, MMP-2 and TIMP1 gene expression." (PMID 36012195, 2022).
duodenal ulcer (2 papers, 2010 to 2023). An ulcer in the duodenal wall. "Combining the MMP-3/TIMP-1 genotype as 6A6A/CC, the risk of duodenal ulcer increased up to 3.6 fold (p < 0.05) in H. pylori-infected females." (PMID 20707923, 2010). "The combined MMP-3/TIMP-1 genotype as 6A6A/CC had a 3.6-fold (p < 0.05) increased risk of duodenal ulcer in H. pylori-infected female." (PMID 20707923, 2010). "Because TIMP-1 genotypes modulated MMP-3 activity, it was further tested whether the MMP-3-1612/TIMP-1372 Combined genotypes contributed to increased risk of duodenal ulcers in females." (PMID 20707923, 2010). "Moreover, TIMP-1 372, as CC, contributes a higher risk of duodenal ulcers to MMP-3 -1612 6A6A." (PMID 20707923, 2010). "The MMP-2/TIMP-1 ratio was higher in patients with simultaneous gastric and duodenal ulcers (P < 0.05)." (PMID 37605137, 2023). "Furthermore, the presentation of the highest levels of MMP-2 and MMP-2/TIMP-1 ratio, along with the lowest levels of TIMP-1 in the coincidence of gastric and duodenal ulcer, raise the presumption of more severe infection in these patients." (PMID 37605137, 2023). "However, the exact reason why such a combined MMP-3/TIMP-1 genotype as 6A6A/CC has just an increased risk of duodenal ulcer in H. pylori-infected females, but not in male, remains uncertain." (PMID 20707923, 2010). "This is the first report to show that there is no direct association between the genotypes of TIMP-1 372 at exon 5 and TIMP-2 at promoter -418, and the presence of gastroduodenal ulcers." (PMID 20707923, 2010). "Although MMP activity is in general counteracted by endogenous tissue inhibitors (TIMPs), there remains no data to check whether TIMP-1 and TIMP-2 SNP genotypes relate to the risk of gastroduodenal ulcer after H. pylori-infection." (PMID 20707923, 2010).
Dupuytren disease (2 papers, 2009 to 2021). "One approach to address this issue would be to investigate whether single nucleotide polymorphisms and other genetic variation in, for example TIMP-1, might explain some of the familial predisposition to Dupuytren's disease." (PMID 19968600, 2009). "The investigators showed elevation of TIMP-1 in the serum of patients with active Dupuytren's disease as compared to carpal tunnel syndrome controls, whereas the levels were similar between patients with inactive late-stage disease and controls." (PMID 19968600, 2009). "One further study has highlighted the key role of TIMP-1 in the pathogenesis of fibrotic changes in Dupuytren's disease." (PMID 19968600, 2009). "In view of TIMP-1 being an important mediator in the pathogenesis of Dupuytren's disease, pharmacological targeting of this protein has been suggested as a possible therapy." (PMID 19968600, 2009). "In view of the strong hereditary component and a predilection for men in Dupuytren's disease, it is interesting to note that TIMP-1 is located on the X-chromosome." (PMID 19968600, 2009).
end-stage renal disease (2 papers, 2014 to 2020). "The highest concentrations of TIMP-1 and TIMP-2 were observed in end-stage renal disease patients and the lowest in I/II CKD patients." (PMID 25145866, 2014).
enteritis (2 papers, 2018 to 2023). Inflammation of the small intestine. "As the MMP-8/TIMP-1 and MMP-9/TIMP-1 ratios were concerned in enteritis patients, significant differences between acute and convalescent samples were detected except for MMP-9/TIMP-1 ratio for Salmonella patients." (PMID 30551610, 2018).
falciparum malaria (2 papers, 2025). "Multiple studies implicate the MMP pathway: serum TIMP-1 and MMP-8 are elevated in falciparum malaria and TIMP-1 correlates with severity, and in pediatric CM retinal MMP-8 locally co-localizes with fibrinogen leak at sites of sequestration, consistent with endothelial barrier disruption." (PMID 41002937, 2025).
Glucose intolerance (2 papers, 2015 to 2024). Glucose intolerance (GI) can be defined as dysglycemia that comprises both prediabetes and diabetes. "Of note, TKO-HFD mice had an overall glucose clearance comparable with that of chow-fed TKO and TWT mice, with a significantly lower blood glucose peak level after 15 and 30 min, suggesting that lack of TIMP-1 protects against HFD-induced glucose intolerance." (PMID 26168159, 2015).
haemorrhage (2 papers, 2015 to 2020). "We aimed to further analyze the association of plasmatic TIMP-1 with the volume of hemorrhage at admission observed in both cohorts by multivariate regression analysis." (PMID 32587306, 2020). "First, in the CHN cohort, the multivariate analysis showed a significant association of TIMP-1 and hemorrhage volume after adjusting for confounding factors in all tested models (models 1 to 3)." (PMID 32587306, 2020). "After finding an association between hematoma volume and TIMP-1, we further explored the effects of TIMP-1 in an experimental model of tPA-induced haemorrhage." (PMID 32587306, 2020).
HCMV infection (2 papers, 2014 to 2022). "A reduction in MMP-9 mRNA, protein, and activity levels but increased tissue inhibitor of matrix proteinases (TIMP)-1 mRNA and protein levels was found after HCMV infection." (PMID 25452935, 2014). "Moreover, HCMV infection alters the MMP-9/TIMP-1 balance in macrophages through immediate-early (IE) gene and late viral gene expression." (PMID 35847899, 2022).
head and neck cancer (2 papers, 2019). A primary or metastatic malignant neoplasm affecting the head and neck. "Similar results regarding the prognostic value of TIMP-1 serum and plasma levels have also been found in various other cancers, including head and neck cancers." (PMID 31240326, 2019). "In numerous reports regarding head and neck cancers, the present correlations are emphasized between the changes in the expression of MMP-2, MMP-9, TIMP-1, and TIMP-2 with tumor progression or its clinical stage." (PMID 31223594, 2019).
hip fracture (2 papers, 2024). Traumatic or pathological injury to the hip in which the continuity of either the femoral head, femoral neck, intertrochanteric or subtrochanteric regions is broken. "Indeed, circulating TIMP-1 levels have been associated with femoral neck bone mineral density (BMD) loss and incident hip fracture in older men." (PMID 37982669, 2024).
hypertensive heart disease (2 papers, 2015 to 2016). Abnormal enlargement of the heart resulting from long-standing hypertension. "Similar to PICP, a positive gradient and a direct correlation exist between the TIMP-1 concentrations in coronary sinus and antecubital vein blood in patients with hypertensive heart disease, but not in normotensive controls." (PMID 27959898, 2016).
Inguinal hernia (2 papers, 2022 to 2023). Protrusion of the contents of the abdominal cavity through the inguinal canal. "In contrast, previous studies have reported a decrease in TIMP-1 levels and an increase in TIMP-2 levels specifically in the serum of patients with inguinal hernias." (PMID 37509159, 2023). "The roles of TIMP-1 and TIMP-2 in the context of inguinal hernias (IHs) have been extensively studied." (PMID 37509159, 2023).
interstitial lung disease (2 papers, 2022 to 2024). A diverse group of lung diseases that affect the lung parenchyma. "Serum PIIINP, TIMP-1, HA, and the ELF score were measured and correlated with clinical variables including the modified Rodnan skin score (mRSS) and interstitial lung disease (ILD)." (PMID 35177989, 2022).
intervertebral disc degeneration (2 papers, 2012 to 2020). "In this study, we used the ADAMTS inhibitor TIMP-1 to treat the model rats with intervertebral disc degeneration, and we found that the levels of the ECM components GAG and HA increased, type I collagen expression decreased, and type II collagen expression increased." (PMID 32855969, 2020). "A dominant imbalance of MMP-3/TIMP-1 and TIMP-2 relative to ADAMTS-4 and ADAMTS-5/TIMP-3 signifies an advanced stage of intervertebral disc degeneration." (PMID 22394620, 2012). "A dominant imbalance of MMP-3/TIMP-1 and TIMP-2 relative to ADAMTS-4 and ADAMTS-5/TIMP-3 is a possible indication of an advanced, irreversible stage of intervertebral disc degeneration." (PMID 22394620, 2012). "Integrated with these reports, our findings show that a state of dominant MMP-3/TIMP-1 and TIMP-2 imbalance relative to ADAMTS-4 and ADAMTS-5/TIMP-3 imbalance may indicate an irreversible stage of intervertebral disc degeneration." (PMID 22394620, 2012).
kidney cancer (2 papers, 2014 to 2020). Primary or metastatic malignant neoplasm involving the kidney. "Future studies should now focus on the mechanism by which TIMP1 regulates the biological process of EMT, perhaps providing a target for the treatment of kidney cancer." (PMID 32420905, 2020).
Left ventricular dilatation (2 papers, 2013 to 2018). Enlargement of the chamber of the left heart ventricle. "Thus, TIMP-1 deficiency has been shown to result in LA and left ventricular dilatation, cardiomyocyte hypertrophy and contractile dysfunction." (PMID 23403858, 2013). "We found that cardiac transcripts of established HF plasma biomarkers, including TIMP1 and galectin-3, were differentially expressed in ISO-treated mouse hearts and correlated with left ventricular dilation compared to the control group." (PMID 30201759, 2018).
leiomyosarcoma (2 papers, 2013 to 2023). An uncommon, aggressive malignant smooth muscle neoplasm, usually occurring in post-menopausal women. "Expression of angiogenin, TIMP1, and TIMP2 was specifically elevated in the PRL3-positive tumor specimens but not in PRL3-negative adjacent normal tissues, with normalized net expression of these angiogenic factors increased in neuroblastoma, leiomyosarcoma, and rhabdomyosarcoma tumors." (PMID 37674627, 2023).
liver failure (2 papers, 2022 to 2024). A liver disease characterized by the liver losing or has lost all of its function. "Our prior studies showed that high circulating levels of osteopontin (OPN) and tissue inhibitor of metalloproteinases 1 (TIMP-1), are major predictors of kidney recovery after LTA in patients with kidney and liver failure." (PMID 39440014, 2024).
Miscarriage (2 papers, 2010 to 2022). A pregnancy that ends at a stage in which the fetus is incapable of surviving on its own, defined as the spontaneous loss of a fetus before the 22th week of pregnancy. "In addition, using anti-inflammatory medication such as lactoferrin was able to prevent miscarriage/abortion by modulating MMP-9/TIMP-1 ratio and promoting repair." (PMID 35622593, 2022).
Mitral stenosis (2 papers, 2014 to 2018). An abnormal narrowing of the orifice of the mitral valve. "The sensitivities of TIMP-1 were comparable between Mitral Stenosis and Mitral Regurgitation patients (AUC = 0.75 in both)." (PMID 24603967, 2014).